STAT1 (signal transducer and activator of transcription 1)
Diseases named in the same sentence as STAT1 in open-access papers (continued):
Sharing a sentence is not in itself a finding about the gene and the disease.
tumor (continued). "From here, we understand the complexity of the cellular response when the JAK/STAT pathway is activated following receptor interaction with different ligands: for example, STAT3 and STAT5A/B are involved in tumor progression, while STAT1 exhibits a tumor-suppressive effect." (PMID 38927059, 2024). "Various STAT signaling pathways, such as STAT3 activation, have been well documented for their tumorigenic role, yet the role of STAT1 in tumor formation remains unclear." (PMID 38675812, 2024). "Most evidence suggests that STAT1 plays an oncogenic role in tumor cells." (PMID 36969076, 2023). "On the one hand, the aberrant expression of STAT1 is found in tumor cells." (PMID 36982677, 2023). "Whereas STAT1 and FAS showed retention of phosphorylated residue regions, this could cause a delay in cell death and prove beneficial for the tumour." (PMID 37091785, 2023). "Moreover, although the significance of STAT1 in tumor biology has been studied for a decade, the observations are still controversial." (PMID 37968576, 2023). "STAT1 is a tumor suppressor whose activation could lead to the overproduction of oxygen species and tumor cell apoptosis." (PMID 37280630, 2023). "Interestingly, we recently reported suppression of STAT1 expression in a tumor microenvironment when Pfn1 is overexpressed in EC." (PMID 37781098, 2023). "First, as noted, many of the cytokines that may be activating STAT3 in the tumor microenvironment are also activating STAT1." (PMID 38022653, 2023). "Tumor cells could also activate cGAMP in STAT1 and NF-κB signaling pathways to form gap junctions with astrocytes and stimulate the latter to produce IFN-γ and other cytokines, which in turn support tumor cell growth." (PMID 36859173, 2023). "In immune cells, STAT1 also acts to suppress tumor development and mediates anti-tumor effects." (PMID 38022653, 2023). "Nevertheless, there were several cancer types that showed opposite conclusions with STAT1, which implied that the specific circumstance might be attributed to certain tumor types and it could assist in guiding treatment in clinical applications." (PMID 36968603, 2023). "Mechanistically, two critical mutations are identified in the E2 and nsP3 genes, which accelerate the entry of M1 virus by increasing its binding to the Mxra8 receptor and antagonize antiviral responses by inhibiting the activation of PKR and STAT1 in tumor cells, respectively." (PMID 37296165, 2023). "Notably, the on‐target inhibition of PARP7 by thioparib‐activated STING/TBK1‐dependent phosphorylation of STAT1, triggered a strong induction of type I interferons (IFNs), and resulted in tumor growth retardation in an immunocompetent mouse model." (PMID 36652375, 2023). "Indeed, a low STAT1/high STAT3 ratio highlighted a faster tumor growth in xenografts compared to high STAT1 and low STAT3 expressions, which were characterized in contrast slower ones." (PMID 36982677, 2023). "Moreover, TAMs can be redirected to M1 phenotype that promotes tumor immune response through NF-κB, STAT1, and STAT3 pathways." (PMID 37241759, 2023). "The M1 type STAT1 macrophage is important in a tumor microenvironment because of its connection with Th1 cells and the secretion of IL-12, a cytokine that maintains Th1 cells sustaining a tumor-eliminating microenvironment." (PMID 37283734, 2023). "However, results from several experimental and clinical studies suggest that STAT1 also functions as a tumor promoter under specific conditions." (PMID 36969076, 2023). "Moreover, we found that IL-11 at least partly inhibited the expression of GPR84 in the tumor microenvironment through the inactivation of STAT1." (PMID 36593458, 2023). "Through tumor-associated myeloid cell subset trajectory inference and SCENIC regulon analyses, our study revealed the emergence of immune deterring myeloid cluster 0 after MCT, which is transcriptionally driven by STAT1 regulon." (PMID 37055410, 2023).
tumor (continued). "Thus, the downstream consequences of (tumor) cell intrinsic STAT1 signaling are highly dependent on the context." (PMID 37561163, 2023). "STAT1, as a transcription factor, plays a significant role in cytokine-mediated signalling pathways that have a range of biological effects such as antiviral activities, suppression of tumour cell growth, and promotion of apoptosis." (PMID 37865727, 2023). "In all, these studies suggest tumor suppressive roles for STAT1 signaling in cancer cells with CIN." (PMID 37561163, 2023). "However, activation of STAT1 usually appears to promote tumor cell apoptosis and anti-proliferative effects." (PMID 36911202, 2023). "Increased STAT1 expression has been fundamentally correlated with tumour suppression." (PMID 36579897, 2023). "STAT1-deficient mice, on the other hand, show decreased T-cell activation and reduced T-cell infiltration of the tumor in response to drug treatment and show resistance to lapatinib and/or DOX’s effects on tumor growth." (PMID 36831326, 2023). "Suppressor of AP‐1 (SAR1), a tumor suppressor, down-regulates the expression of p-STAT1 and STAT1 in CAC cells, inhibits the activation of MCP-1/CCR2 axis, reduces macrophage infiltration, which may inhibit the tumorigenesis of CAC." (PMID 37006260, 2023). "Reflecting the context-dependence in transcription factor function, it should be noted that in certain conditions STAT1 may function as a tumor driver." (PMID 38022653, 2023). "Similarly, inhibition of receptor-interacting serine threonine kinase 1 (RIPK1) enhanced STAT1 signalling and the activation of cytotoxic T cells contributing to anti-tumour activity." (PMID 37752135, 2023). "In addition, it has been shown to have anti-tumor effects through signaling in mesenchymal stromal cells (MSCs), although this occurs following the switching of STAT1 homodimers to STAT1:STAT2 heterodimers in response to interferon-α (IFNα)." (PMID 37173951, 2023). "Tumor cell gene expression also changed significantly in mANK-101–treated animals, with increased Stat1, Cxcl9, and Cxl10 (all consistent with IFN-γ signaling), as well as increases in Cd74, MHC alleles, and proteasome components, indicating increased antigen processing and presentation." (PMID 38063196, 2023). "Thus, we found that PARP14 pharmacological antagonism or silencing in tumour cells enhanced STAT1 phosphorylation and expression of STAT1 target gene products, including IRF1 responsible for the expression of many IFNγ signalling genes but also PARP14 itself." (PMID 37752135, 2023). "In the context of cancer, STAT1 possesses both tumor-suppressive and tumor-promotive activities." (PMID 37968576, 2023). "Recent studies showed that homeobox D9 (HOXD9) can increase cell metastasis through the TGF-β1-induced EMT63, and the NMYC interactor (NMI) can upregulate signal transducer and activator of transcription 1 (STAT1) and then promote tumor cell proliferation via the TGF-β/Smad pathway." (PMID 36927770, 2023). "A recent study has shown that the RSI is associated with immune response in a large sample of tumours, which is not unexpected given the inclusion of STAT1 and IRF1." (PMID 37444614, 2023). "Similarly, immune/inflammation-related TFs, such as NFKB2, STAT1, and RELA, and FOXO3, showed high activity in CXCL10+MEL and TMSB4X+MEL subclusters, which underlies the immunomodulatory phenotype of tumor cells." (PMID 38065972, 2023). "Furthermore, increased expression of STAT1 and STAT3 in tumor tissue implicated adverse prognosis whereas higher STAT4 or STAT5 expression meant improved survival." (PMID 36968603, 2023).
tumor (continued). "STAT1 and STAT4 are genes located on the 2q32 band, which encode for important components of the JAK-STAT signaling pathway, which is (among other processes) involved in apoptosis and oncogenesis, having both tumor suppressive and tumor promoting functions." (PMID 36982172, 2023). "In alignment with this tumor suppressive role of STAT1, an in vivo genome-wide transposon mutagenesis screen revealed that specifically tumors that display CIN inactivate inflammatory signaling through STAT1 inactivation in combination with increased c-Myc activity compared to euploid tumors." (PMID 37561163, 2023). "Thus, it would be very important to understand how STAT1 signaling is influenced by anti-tumor treatment with JAK inhibitors." (PMID 38022653, 2023). "In addition, IFN-α treatment of patients with cutaneous melanoma significantly modulates the balance of STAT1/STAT3 in tumor cells and host lymphocytes." (PMID 37047709, 2023). "Furthermore, STAT1 knockdown (a signaling component of IFN-γ) in SCC cells suppressed tumor cell invasion in the subcutaneous tumor transplantation model." (PMID 35159384, 2022). "Taken together, STAT1 and STAT3 signaling pathways are tightly interconnected and IFN-γ/STAT1 target genes may be activated in a proinflammatory IL-6-containing tumor microenvironment." (PMID 35267462, 2022). "We therefore hypothesized that increased T-cell chemokine expression upon ablation of SPATA2 or CYLD is driven by elevated IFN-γ-STAT1 signaling in tumor cells." (PMID 36531014, 2022). "The role of tumour-derived STAT1 in promoting of PD-L1 expression, however, is more evident." (PMID 35595823, 2022). "Loss of YTHDF1 mediated the overexpression of IFN-γ receptor 1 and JAK/STAT1 signaling pathway in tumor cells, which might contribute to restored sensitivity to antitumor immunity." (PMID 35193930, 2022). "This represents a major gap in our knowledge of STAT1 activation by HNSCC cells in the tumour microenvironment, which is essential to advance our mechanistic understanding of the role of STAT1 in HNSCC, and design therapies that exploit the STAT1 pathway in HNSCC treatment." (PMID 35595823, 2022). "There is also increasing evidence supporting the tumor-promoting functions of STAT1." (PMID 35313878, 2022). "HLJ1 reportedly serves as a tumor suppressor and inhibits the proliferation, migration and invasion of cancer cells by regulating the STAT1/p21 pathway and could thus be a biomarker for cancers." (PMID 35216179, 2022). "STAT1:STAT3 heterodimerization hampers the anti-tumor M1 phenotype." (PMID 35406557, 2022). "We further found, using the 4NQO murine model of HNSCC, that STAT1 signalling is essential for PD-1/PD-L1 expression in the tumour microenvironment and by immune cells, including the accumulation of immunosuppressive populations during head and neck carcinogenesis." (PMID 35595823, 2022). "This analysis identified a motif for STAT1:STAT2 as the most highly enriched motif, providing evidence that the down-regulation of the mRNAs encoding STAT1 and STAT2 is functionally related to genes exhibiting reduced expression in the Ly6C monocytes of tumor-bearing mice." (PMID 35159100, 2022). "Like the STING pathway, the STAT1 pathway is a major contributor to the anti-tumor immune response." (PMID 36276148, 2022). "By performing our analyses specifically within the stroma-rich/high-fibroblast (HiFi) subtype of CC, we identify and validate the clinical value of a HiFi-specific prognostic signature (HPS), which stratifies tumours based on STAT1-related signalling (High-HPS v Low-HPS=HR 0.093, CI 0.019 to 0.466)." (PMID 35477539, 2022). "We observed that in the absence of STAT3, IL-6 induced the activation of STAT1 and its target genes suggesting that IL-6 derived from the tumor microenvironment may activate both STAT1 and STAT3 target genes in HCC tumor cells." (PMID 35267462, 2022).
tumor (continued). "Therefore, mutations and deletions of proteins associated with this pathway on tumor cells, such as JAK1 and JAK2, STAT1, IRF1, and other IFN receptor chains, can lead to drug resistance to immunocheckpoint inhibitors." (PMID 36185620, 2022). "STAT1 is important in anti-tumour immune responses against HNSCC." (PMID 35595823, 2022). "EEF1A1 can promote tumor spread through the STAT1-cyclin D1 pathway." (PMID 35126520, 2022). "In addition, M1 macrophages secrete CXCL9, CXCL10 and CXCL15 chemokines upon STAT1 signaling, which recruit cytotoxic T lymphocytes (CTLs) to the tumor." (PMID 36311701, 2022). "It suggests that tumor inhibition of SHF probably underlies the regulation of STAT1 independent of STAT3, a question worthy of further exploration." (PMID 35843865, 2022). "However, many previous studies have confirmed that STAT1 is a tumor suppressor gene that is related to the formation and metastasis of many tumors and plays an important role in regulating tumor cell proliferation, survival, and angiogenesis." (PMID 35821222, 2022). "More importantly, FAK was found to function downstream of αVβ3 integrin to positively regulate the interferon signaling, and then promote the nuclear translocation of transcription factor STAT1/2, thereby activating PD-L1 expression and promoting tumor immune escape." (PMID 35425701, 2022). "The accumulation of HIF-1α due to DOX induction in cells is caused by increased expression and activation of Signal transducer and activator of transcription 1 (STAT1) where this activation will stimulate the expression of iNOS and its NO synthesis in tumor cells." (PMID 35340325, 2022). "Therefore, we demonstrate that suppression of histone deacetylation and DNA methylation restores epigenetically silenced tumor suppressors such as MEG3, P16, PTEN and STAT1, resulting in inhibition of tumor cell growth." (PMID 35646715, 2022). "Knockout of STAT1 in CRC cells reduced tumor growth in vivo." (PMID 35313878, 2022). "In summary, our HiFi-specific analyses identified that elevated expression of HPS, which distinguished primary tumours based on IFN-alpha, IFN-gamma and STAT1-related biological signalling, was significantly associated with disease relapse specifically within stroma-rich CC." (PMID 35477539, 2022). "Since STAT1 is known to be important in the antitumor immune reaction through induction of IFNγ secretion, inhibition of STAT1 via JAK1 or JAK2 may result in reduced anti-tumor clearance." (PMID 36263134, 2022). "In addition to promoting carcinogenesis, STAT3 activation can block STAT1-mediated tumor suppression." (PMID 36439472, 2022). "Therefore, to determine the impact of tumour-derived STAT1 on HNSCC tumour development in vivo, we used the oral carcinogen 4NQO to induce oral carcinogenesis in both Stat1+/+ and Stat1−/− mice." (PMID 35595823, 2022). "Because M-MDSCs are known to facilitate the epithelial-to-mesenchymal transition that precedes metastasis, tumour-derived STAT1 may be a predictor of immune suppression and metastasis in HNSCC." (PMID 35595823, 2022). "Effective tumor infiltrating lymphocytes (TILs) activate Th1-associated pathways such as the interferon-γ/Janus kinase/signal transducer and activator of transcription 1 (IFN-γ/JAK/STAT1)–mediated signaling pathway, which leads to increased expression of immune checkpoints on tumor cells." (PMID 35410311, 2022). "STAT1 is considered to be a tumor suppressor while STAT3 is rather seen as an oncogene." (PMID 35267462, 2022). "Furthermore, the expression of STAT1 in patients with CRC was found to be significantly related to the tumor stage." (PMID 36061181, 2022). "Similarly, the mechanism of anticancer potential is plausibly mediated through upregulation of STAT1 gene (tumor suppressor), and downregulation of IL-6, TNF-α, and CD40 (tumor causing genes) besides other intricate mechanisms." (PMID 36612248, 2022). "This suggests that the anti-tumor activity of STAT1 is cell autonomous." (PMID 35681772, 2022).
tumor (continued). "Current studies have confirmed that STAT3-mediated inhibitory tumor immune response has an antagonistic effect on STAT1-driven antitumor immune response, which may lead to the loss of function of the IFNγ/JAK/STAT1 pathway." (PMID 36185620, 2022). "A few reports have postulated that the isoforms of STAT1 could be differentially activated owing to either suppression or tumor progression." (PMID 35406434, 2022). "In light of our results, we hypothesize that upregulation of PD-L1 expression via STAT1 activation in gastric epithelial transformed cells suppresses anti-tumor immune responses of CD8+ cytotoxic T cells." (PMID 35456965, 2022). "STAT1 signaling promotes T helper 1 (Th1) differentiation and interleukin-12 receptor (IL-12) expression, and thus, in some context, has a role in the anti-tumor immune response." (PMID 35603163, 2022). "CPVL may promote human tumor progression by inhibiting STAT1 pathway through interacting with BTK/p300 axis." (PMID 36479092, 2022). "When analyzing tumor prognosis, CD8+ T cell immune infiltration and STAT1 were identified to be independently associated with prognosis (HR [95%CI] = 0.41 [0.18–0.93] for CD8 + T cell immune infiltration, and HR [95%CI] = 1.96 [1.07–3.57] for STAT1 expression)." (PMID 35456965, 2022). "Preclinical studies demonstrated that IFN-γ resulting IDO1/aryl hydrocarbon receptor (AhR) dependent p27 induction could prevent STAT1 signaling, thus suppressing the process of tumor cell death and activating tumor dormancy program." (PMID 36032151, 2022). "Pathway analysis of RNA sequencing data from tumours from Stat1+/+ and Stat1−/− mice orthotopically injected with LY2 HNSCC cells also identified TRIM24 as the top predicted negative transcriptional regulator of STAT1 during HNSCC in our data set (z score –5.804, p value 1.32 × 10−16)." (PMID 35595823, 2022). "Most studies have suggested that STAT1 is a tumor suppresser." (PMID 35515130, 2022). "Our study found seven downstream factors that may be associated with chemoresistance, LTF, SOD2, STAT1, CDKN2A, CD81, RAC1, and NDRG1 and five factors that may be associated with tumor development, CCN1, DCTN3, MUC1, H1-5, and SLC1A5." (PMID 35421932, 2022). "In spite of this, STAT1 is typically regarded as a tumor suppressor." (PMID 36439472, 2022). "Given the important role of STAT1 activation in tumor metastasis, we then investigated whether LSECtin could modulate STAT1 phosphorylation." (PMID 35821222, 2022). "Existing studies have confirmed that the STAT3-mediated inhibitory tumor immune response pathway has an antagonistic effect on the STAT1-driven antitumor immune response, which may lead to the loss of IFNγ/JAK/STAT1 pathway function." (PMID 36185620, 2022). "PD-L1 expression was reduced among CD11b+ cells in the tumours of Stat1−/− mice." (PMID 35595823, 2022). "Thus, TRIM24 presents itself as a potential target for modulating STAT1 expression in the tumour microenvironment." (PMID 35595823, 2022). "Baicalin can reduce the m6A modification level of HKDC mRNA by inhibiting METTL3, which leads to the decrease of HKDC expression and the upregulation of HKDC/JAK2/STAT1/caspase-3 signaling pathway, and finally inhibits the invasion and metastasis of tumor cells." (PMID 35784761, 2022). "IFN-γ is mainly produced by T cells, NK cells and NK T cells, and IFN-γ signal must be activated through JAK1/2/STAT1 pathway, suggesting that IFN-γ/JAK1/2/STAT1 pathway may be involved in anti-tumor immune response." (PMID 35740594, 2022). "STAT1 signalling even has anti‐tumour activity in different models." (PMID 35689379, 2022). "One study demonstrated a negative correlation between METTL3 or METTL14 and STAT1 in patients with low mutational tumor burden and tumors associated with the mismatch-repair-proficient or microsatellite instability-low (pMMR-MSI-L) genotypes." (PMID 35885000, 2022).